AFP (alpha fetoprotein)
Diseases named in the same sentence as AFP in open-access papers (continued):
Sharing a sentence is not in itself a finding about the gene and the disease.
tumor (continued). "Univariate and multivariate Cox regression analyses confirmed that tumor diameter, AFP levels, and SHRPI were independent risk factors for RFS in HCC after LT." (PMID 41050691, 2025). "Although mammals express four hexokinase isoforms, overexpression of HK2 is notably linked to aggressive tumor features—including larger tumor size, lymph node metastasis, advanced cancer stages, and elevated alpha‐fetoprotein levels." (PMID 40365984, 2025). "Some studies link these mutations to less aggressive tumours, lower alpha-fetoprotein levels, and better differentiation, while others associate them with worse outcomes, such as vascular invasion, or find no significant impact on survival." (PMID 40650279, 2025). "Elevated AFP levels are increasingly being associated with tumor progression, angiogenesis, metabolic reprogramming, immune evasion, and drug resistance in several malignancies." (PMID 40430002, 2025). "Alpha-fetoprotein and liver fibrosis reflect tumor biology and underlying liver health, respectively." (PMID 41256539, 2025). "The ATSI score was developed from two independent prognostic risk factors: baseline AFP ≥ 400 ng/ml (HR 1.73, 95% CI 1.01–2.96, P = 0.046) and initial tumor shape irregularity (HR 1.94, 95% CI 1.03–3.65, P = 0.041)." (PMID 39714631, 2025). "Among tumor markers, elevated AFP was strongly associated with HCC (OR = 2.7, 95% CI: 2.0–3.5, P < .001), while elevated CA19-9 significantly increased ICC risk (OR = 4.1, 95% CI: 3.0–5.6, P < .001)." (PMID 40128070, 2025). "At a local hospital, a diagnostic workup excluded Hepatitis B and C, while tumor markers, including alpha-fetoprotein (AFP) and carcinoembryonic antigen (CEA), were within normal limits." (PMID 41458624, 2025). "The area under the curve (AUROC) was used to evaluate the diagnostic efficiency of PIVKA-II and the combined tumor markers with AFP." (PMID 38622445, 2024). "The association between NLR and conventional tumor markers of tCa (AFP, B-HCG, and LDH) was evaluated in four studies." (PMID 39465013, 2024). "Univariate analysis demonstrated that STIP1 and tumor markers log AFP and DCP were associated factors of HCC, whereas multivariate logistic analysis showed STIP1 and DCP as independent predictors of HCC." (PMID 38780206, 2024). "Despite these findings, understanding AFP's role in tumor progression and its underlying mechanisms remains incomplete." (PMID 39135041, 2024). "The major findings of this study revealed that high tesmin expression was significantly associated with advanced tumor stage, poorer differentiation, higher serum AFP levels, and positive vascular invasion." (PMID 38283987, 2024). "A baseline AFP ≥ 20 ng/mL was associated with tumor dimension ≥ 5 cm (p = 0.008) and histological tumor grading G3 (p < 0.001)." (PMID 38792876, 2024). "In the present study, we also confirmed previously reported risk factors for the prognosis in HCC patients: tumor size, AFP, DCP, INR, and NLR." (PMID 39513118, 2024). "Studies have established that both baseline AFP levels and post-treatment decline in serum AFP are associated with tumor response in patients receiving various systemic therapies, such as anti-angiogenic therapy and resection." (PMID 39767676, 2024). "Multivariate analysis demonstrated that only TIGIT expression (p = 0.047), tumor size (p = 0.018), and AFP level (p = 0.015) were identified as independent risk factors influencing postoperative OS." (PMID 39540362, 2024). "The results indicated that increased RGS19 expression was positively associated with increased tumor size (p = 0.014), increased AFP levels (p = 0.003) and advanced TNM stage (p = 0.014)." (PMID 38825640, 2024). "Tumor characteristics, such as size >5 cm, multifocality, vascular invasion, and high alpha-fetoprotein (AFP) levels, are associated with poor prognosis." (PMID 39682279, 2024).
tumor (continued). "Low levels of CXCR1 and CXCR3 are associated with a decreased tumor volume, decreased alpha fetoprotein levels, and a decreased TNM tumor stage 110." (PMID 38481800, 2024). "Imaging examinations and the tumor marker AFP are the most widely used diagnostic methods worldwide, yet they have limited accuracy in detecting HCC." (PMID 39677962, 2024). "For PFS, univariate analysis suggested associations with BCLC stage, VP4 complicated with tumor exceeding 50% of liver, extrahepatic metastasis, AFP ≥ 400 ng/mL, and prior locoregional therapy in these patients with highly advanced HCC." (PMID 38530254, 2024). "Previous studies on prognostic factors for mortality in sorafenib-treated HCC patients have focused on tumor-associated factors, including extrahepatic metastasis, vascular invasion, high alpha-fetoprotein levels, and unfavorable liver function." (PMID 38275895, 2024). "It is generally believed that HCC recurrence within 2 years after the surgery are mainly caused by residual tumor cells, which are mostly related to tumor characteristics, including diameter, invasiveness, and serum alpha fetoprotein levels." (PMID 39286273, 2024). "Elevated tumor markers, such as AFP and β-HCG, are associated with a higher risk of recurrence and aggressive disease behavior." (PMID 39677122, 2024). "Due to their origin from primordial germ cells, nearly all YST patients exhibit positive expression of serum AFP, which is a fundamental diagnostic tool and prognostic indicator for the tumor." (PMID 38966065, 2024). "Of the clinical factors, the results of univariate and multivariate analyses showed that serum AFP level and tumour size were both significant risk factors for MVI, which was consistent with previous reports." (PMID 38281008, 2024). "Consistent with other studies, the MVI rate, tumor differentiation grade, high AFP value, and long cold ischemia time were associated with high recurrence rates in our study." (PMID 39281373, 2024). "In our study, we observed significant associations between both nomograms and tumor characteristics, as well as AFP levels." (PMID 38773511, 2024). "Intriguingly, we discovered a significant association between reduced TRIM55 expression and larger tumor size (p = 0.008) as well as elevated serum alpha-fetoprotein (AFP) levels (p = 0.026)." (PMID 39420007, 2024). "Considering that the elderly are at high risk for tumors, we also measured the levels of the tumor-related markers AFP and CEA in these samples." (PMID 38698420, 2024). "In summary, we describe an unusual case of WT, associated with substantially raised serum AFP at diagnosis which rose further during pre-operative chemotherapy, and fell rapidly upon tumor resection." (PMID 38098239, 2024). "Elevated serum tumor markers, such as AFP and β-HCG, are frequently associated with poorer prognosis, given their indication of more aggressive disease." (PMID 39727674, 2024). "Kaplan–Meier (KM) curve analysis indicated that a favorable early AFP response is not only associated with a lower risk of early tumor progression but is also closely linked to long-term survival benefits for patients." (PMID 39767676, 2024). "This reduction in AIM2 was strongly associated with higher serum AFP levels, vascular infiltration, poor tumor differentiation, incomplete tumor envelope, and unfavorable odds of survival after surgery." (PMID 39450183, 2024). "High levels of AFP (P = .002) and low levels of tumor-infiltrating N1 neutrophils (P = .006) were associated with poor RFS." (PMID 38986528, 2024). "The diagnostic results of a complete blood count, tumor markers like AFP, HCG, and LDH, and chest x-ray were within normal limits." (PMID 39013244, 2024).
tumor (continued). "The diminished levels of TRIM55 were significantly associated with larger tumor size and elevated serum AFP levels." (PMID 39420007, 2024). "In this study, we discovered that upregulated RGS19 expression is significantly associated with tumor size, AFP level, OS, and PFI in patients with HCC." (PMID 38825640, 2024). "Serum AFP levels as a marker for HCC have been shown to be associated with factors of tumour aggressiveness including MVI and differentiation." (PMID 38281008, 2024). "Sarcopenia, maximal tumor diameter, and AFP ≥ 200 ng/mL were independent risk factors for OS and PFS." (PMID 38434977, 2024). "The data presented that high expression of RNF214, tumor recurrence, and abnormal AFP levels were independent risk factors for HCC prognosis." (PMID 38969650, 2024). "The elevation of tumor markers, mainly AFP, is independently associated with poor prognostic features, such as shortened survival." (PMID 38438972, 2024). "In the subsequent analysis, we examined the prognostic value of KLRB1 expression on CD8 T cells and NK cells within the low-risk subgroup of HCC patients (defined as AFP < 400 ng/mL, single tumor, tumor size < 5 cm and BCLC 0 + A)." (PMID 38914941, 2024). "Univariate analysis identified macrovascular invasion, intrahepatic tumor numbers > 10, alpha–fetoprotein (AFP) levels > 400 ng/mL, and CPS classes B and C as risk factors for progression, while a prior response to anti-PD-1 therapy was protective." (PMID 39580565, 2024). "One of the methods for predicting LT outcome is the Metroticket 2.0 model, which is based on the level of alpha-fetoprotein (AFP), tumor size, and tumor number and allows the prediction of the risk of death from HCC-related factors after LT." (PMID 39597777, 2024). "In multivariate analysis, A/A genotype, alpha‐fetoprotein level, and number of circulating tumor cells were associated with microscopic portal vein invasion (p = .01.01, and <.01)." (PMID 38798075, 2024). "Serum AFP has been found useful in selecting candidates for liver transplantation and predicting the risk of tumor recurrence after liver surgery." (PMID 39583507, 2024). "Approximately 42% of patients exhibited Tyro3 overexpression in tumor tissues (>2-fold) and high Tyro3 expression was significantly associated with higher levels of alpha-fetoprotein (AFP)." (PMID 38298195, 2024). "In this study, multivariate analyses identified CTP stage A, ALBI grade 1, tumor number ≤ 3, and treatment regime as risk factors influencing OS, while AFP level, tumor number, metastasis, and treatment regime were considered as risk factors affecting PFS." (PMID 38717693, 2024). "Larger tumor size and higher AFP levels were associated with more liquefaction necrosis in the tumor." (PMID 39161764, 2024). "These TKIs improved patients survival, which are associated with disease stage, etiology, liver function, tumor burden, baseline levels of alpha-fetoprotein, and treatment history." (PMID 38960980, 2024). "This study demonstrated that ROR2 negativity determined by immunohistochemical staining was significantly associated with high AFP and low tumor differentiation in HCC." (PMID 37814183, 2024). "In the current study, we found that DCAF8L1 was significantly increased in HCC tissues campare to para-carcinoma tissues and positively associated with tumor aggressiveness, including OS rate, T stage and AFP level." (PMID 38649860, 2024). "As further support, in our immunohistochemical staining of ROR2 in 243 HCC cases, ROR2 negativity was significantly associated with high level of AFP (P = 0.006) and poor differentiation (P = 0.015), which correlated with tumor differentiation." (PMID 37814183, 2024). "A high expression of CDCA8 has been associated with higher AFP, larger tumor size, pathological status, T stage, and poor prognosis in HCC." (PMID 38742112, 2024).
tumor (continued). "The presence of ≥4 tumors was assigned three risk points, whereas tumor size ≥10 cm, Child–Pugh class B, serum AFP ≥400 ng/mL, and tumor rupture were each assigned two risk points." (PMID 37346065, 2023). "Results showed that DHX37 expression was associated with AFP (ng/mL) (p = 0.005), tumor status (p = 0.009), residual tumor (p = 0.017), vascular invasion (p = 0.035), and histologic grade (p = 0.019)." (PMID 37958405, 2023). "This study suggested that AFP response to LRT can be used to stratify the tumor recurrence risk after LDLT in HCC patients with abnormal pre-LRT AFP levels." (PMID 36900345, 2023). "To compare the prognostic performance of the MVFC‐identified tumor mutations and known biomarkers including post‐operative AFP and DCP, we first used univariate cox analysis to screen clinical features and biomarkers with prognostic value." (PMID 37496285, 2023). "Multiple factors, including advanced tumor stage and viral etiology of chronic liver disease, are associated with elevated AFP levels in HCC patients." (PMID 36831565, 2023). "Multi‐variate cox analysis further revealed that post‐operative detection of MVFC‐identified tumor mutations, alcohol, AFP and BCLC were independent risk factors of RFS." (PMID 37496285, 2023). "The objective of this study was to evaluate a composite biomarker of EpCAM-positive circulating tumor cells and serum AFP to identify patients at high risk of early recurrence within 2 years after liver resection." (PMID 38012205, 2023). "AFP is a translation product of the albuminoid gene family and is characterized as an embryo-specific glycoprotein that is associated with a tumor." (PMID 37466839, 2023). "Serum AFP level > 400 ng/mL was the only laboratory indicator significantly associated with poor tumor differentiation in our study, which was in line with existing evidence." (PMID 36617583, 2023). "Several studies have shown that positive tumor PD‐L1 expression is associated with more aggressive biological behaviors (such as high serum AFP levels, poor differentiation, and vascular invasion)." (PMID 36965092, 2023). "On the other hand, MCSF was inversely associated with HBV-DNA, HBeAg−, abnormal AFP and tumor number in HBV-HCC patients." (PMID 35347503, 2023). "Systemic immune-inflammation index–albumin-bilirubin 2 category was associated with relatively higher AFP levels, bigger largest tumor size, more BCLC C stage, and worse OS." (PMID 36620927, 2023). "In the COR group, Cox analysis results showed AFP, tumor size, N stage and M stage were independent risk factor of OS." (PMID 37409255, 2023). "This risk classification is based on anatomical risk factors as well as tumor marker levels of AFP, HCG, and LDH assessed pre‐chemotherapy after orchiectomy treatment." (PMID 37392170, 2023). "Distant organ metastasis, lymph node metastasis, chemotherapy, AFP positive, histological grade, sex, race, tumor size, and age were risk factors for HCC." (PMID 37035138, 2023). "Elevated SKA1 expression in HCC is associated with advanced clinicopathological features (AFP, histological grade, pathological stage, T stage, and tumor status), poor prognosis, and survival time." (PMID 37746945, 2023). "In the univariable Cox regression analysis, we found that out of the up‐to‐11 criteria, better tumor response, decrease of AFP and eGFR were significantly associated with better PFS." (PMID 37278402, 2023). "AFP is the most widely used marker for HCC surveillance due to its close association with tumor differentiation, vascular invasion, and progression of HCC tumors." (PMID 37760434, 2023). "Male gender, increasing numbers of tumors, bilobar distribution, larger tumor size, and increasing AFP were associated with increased discrepancy." (PMID 37326440, 2023).
tumor (continued). "Albumin was reported to have a potential role in inhibiting the HCC growth; thus, lower albumin was associated with larger tumor diameters, more tumor multifocality, and higher AFP levels." (PMID 38138039, 2023). "Previous studies have shown that elevated AFP values are associated with higher tumor burden, invasiveness, HCC recurrence, and poor prognosis across all stages of HCC." (PMID 37762018, 2023). "Regarding to this, previous studies have shown that AFP and MiVI were both associated with aggressive tumor behaviors in both ICC and HCC,8, 9 and HCC can arise from satellite nodules which are that result from MiVI." (PMID 36354141, 2023). "The foremost is that ctDNA is tumor-specific, enhancing its reliability as a marker of disease status or to identify the nature of the tumor, in contrast to AFP, which is tumor-associated." (PMID 38201440, 2023). "Studies have shown that the prognosis of EGCTs is associated with the histological type of the tumor and the expression of tumor markers (AFP and β-HCG)." (PMID 37138865, 2023). "In summary, the AFP score 2 model classified the risk of tumor recurrence more appropriately than the other two models in the present cohort." (PMID 36967432, 2023). "Close AFP monitoring and especially the ratio of maximum AFP to post-chemotherapy AFP values can help to predict the risk of tumor recurrence after transplantation." (PMID 36832331, 2023). "For decades, AFP has been widely used as a tumor marker in the surveillance of populations at high risk of developing HCC, but some limitations are well known." (PMID 36899960, 2023). "In the MVI risk estimation nomogram, large tumor size and high serum levels of AFP and GGT concentrations have been reported to increase the possibility of MVI in HCCs." (PMID 38049860, 2023). "Competing-risk analysis results showed AFP, tumor size and M stage were independent risk factor of CSS." (PMID 37409255, 2023). "Univariate Cox analysis showed that TAFP, TBIL, AFP, KI-67, tumor size, MVI and the PA-TACE timing were risk factors for RFS in HCC patients." (PMID 36969018, 2023). "For HCC, CTC-WBCs in blood were significantly associated with larger tumor size and higher AFP levels." (PMID 38087278, 2023). "High ADAM17 expression was linked to poor tumour/node (T/N) stage and alpha fetoprotein (AFP) levels." (PMID 38069391, 2023). "The relationship between NLRP6 expression and clinical features of LIHC was investigated, and the findings revealed that NLRP6 expression was significantly associated with age, race, tumor grade, AFP level, and OS event." (PMID 35651286, 2023). "Logistic regression analysis revealed that SKA1 expression levels in HCC tissues were strongly linked to T stage, tumor status, histologic grade, age, and AFP levels." (PMID 37746945, 2023). "Previous studies have shown that the prognosis of NBNC-HCC is associated with some factors, such as AFP level, liver fibrosis, tumour size, and ductal invasion." (PMID 35293607, 2023). "Several present studies have increasingly showed that the AFP level was closely associated with the cellular differentiation, microvascular invasion, and tumor prognosis." (PMID 36816925, 2023). "We included five significant clinical risk factors (age, preoperative serum tumour markers AFP and B-HCG, histotype and BMI) to build the clinical model." (PMID 38067334, 2023). "A tumor size ≥ 3 cm, AFP > 400, and ascites were associated with a poor progression-free survival among young patients." (PMID 36902673, 2023). "The ROC analysis further confirmed this, demonstrating that ITGA6 has a strong diagnostic power for distinguishing HCC from non-tumor conditions, even exceeding the value of traditional biomarker, AFP." (PMID 37627184, 2023). "It was found that age, T, N, M stage, tumor diameter, and AFP were risk factors that influenced the post-operative survival time of the patients." (PMID 36841760, 2023).